MLLT10 (MLLT10 histone lysine methyltransferase DOT1L cofactor)
Diseases named in the same sentence as MLLT10 in open-access papers (continued):
Sharing a sentence is not in itself a finding about the gene and the disease.
tumor (9 papers, 2002 to 2024). "After IHC staining of the tumor, the expression of caspase 3 was significantly increased after sh-Lnc-S100B-2 and sh-MLLT10 treatment." (PMID 35126515, 2022). "Tumor volume and mass were significantly reduced after inhibition of Lnc-S100B-2 and MLLT10." (PMID 35126515, 2022). "The expression of Lnc-S100B-2 and MLLT10 was altered in the tumor." (PMID 35126515, 2022). "It is suggested that Lnc-S100B-2 might affect the EMT of tumor cells through MLLT10, at least partially." (PMID 35126515, 2022). "Interestingly, parallel evolutionary patterns were exhibited in the phylogenetic trees, including mutations in MLLT10, WDR5, and ERMARD, which indicated the diversity of tumor genome evolution." (PMID 33078899, 2020). "Five fusions found exclusively in tumour samples could be considered pathogenic (NFYG-TAL1, RIC3-TCRBC2, SLC35A3-HIAT1, PICALM MLLT10 and MLLT10-PICALM)." (PMID 30914738, 2019). "To further explore the role of Lnc-S100B-2 and MLLT10 in CRC, we investigated the immune cell invasion and the degree of EMT in the tumor." (PMID 35126515, 2022). "CNGs associated with poor outcome harboured transcription factors GATA3, GATA5, MLLT10, and TAF3 frequently amplified in HBCs15,19,28,41–43, EMT markers VIM, LAMA5, and ZEB121, and several genes enriching biological processes enhancing tumour-cell migration and motility." (PMID 31969654, 2020). "Interestingly, expression of most of the fusion partners including the high‐frequency partners like AFF1, MLLT1, MLLT3, MLLT10, ELL, and MLLT4, were positively correlated with MLL1 expression irrespective of the tumor type." (PMID 30548174, 2019).
blood cancers (2 papers, 2021 to 2024). "Human AF10 (or mixed-lineage leukemia translocated to 10 (MLLT10)) is essential in hematopoiesis and implicated in blood cancers." (PMID 34226546, 2021).
MLLT10 also shares sentences with these, for which no sentence is quoted: acute lymphoblastic leukemia (10 papers); malignant lymphoma (5); Acute Monoblastic Leukemia (2); asthma (1); B-cell acute lymphoblastic leukemia (1); bone marrow disease (1); central nervous system leukemia (1); Down syndrome (1); erythroleukemia (1); Fanconi anemia (1); hematological disorders (1); hyperglycerolemia (1); Langerhans cell histiocytosis (1); leukocytosis (1); lymphoblastic lymphoma (1); Meconium ileus (1); megakaryoblastic leukemia (1); multiple lipomatosis (1); ovarian carcinoma (1); retinoblastoma (1); rheumatoid arthritis (1); transient myeloproliferative disorder (1); type 2 diabetes (1).